USP5 (ubiquitin specific peptidase 5)
Diseases named in the same sentence as USP5 in open-access papers (continued):
Sharing a sentence is not in itself a finding about the gene and the disease.
tumor (continued). "Moreover, the relationship between USP5 and PARP1 was tested in the mice model with a subcutaneous tumor." (PMID 37060095, 2023). "Importantly, USP5 inhibition in combination with the MEK inhibitor, Trametinib, or anti-CTLA-4 antibodies has an additive effect on suppressing tumor growth in mice." (PMID 37208329, 2023). "Our findings indicate an antagonistic role of Leon/USP5 in Atg1/ULK1-mediated autophagy and may provide mechanistic insights into how USP5 promoted tumor growth and progression." (PMID 37607937, 2023). "Moreover, western blot for detecting the expression level of USP5 in six pairs of HCC tissues and para‐tumor tissues further demonstrated that USP5 was significantly higher in tumor tissues." (PMID 37492786, 2023). "Moreover, tumors from Usp5 cKO mice treated with Trametinib displayed reduced PD-1 expression and elevated IFN-γ, TNFα, and GzmB in tumor-infiltrating CD8+ T cells." (PMID 37208329, 2023). "However, inhibition of USP5 or ERK can reverse this process to destabilize PD-1 and activate CD8+ T cells, resulting in suppressing immune evasion and tumor growth." (PMID 37208329, 2023). "Therefore, considering such an important effect of β-catenin, the expression of β-catenin is highly expressed in patients with USP5-high NSCLC and correlated with tumor metastasis." (PMID 32477134, 2020). "Since a broad range of tumor types express DR4 and DR5, those regulated by DR4, DR5 may be good targets for USP5 inhibition." (PMID 31645897, 2019). "However, USP5 deficiency did not affect IFN-I response in tumor cells because neither p-STAT1 and p-STAT2 levels nor IFN-stimulated gene expression were changed in USP5-depleted cells." (PMID 41321309, 2025). "Future research should further explore whether YBX3 is influenced by other molecular chaperones or regulatory factors, and investigate the structural basis of the USP5/YBX3 interaction and its dynamic regulation in the tumor microenvironment to promote clinical translation." (PMID 41213937, 2025). "To further verify the involvement of ferroptosis in USP5-mediated tumor regulation, we measured the expression levels of two key markers of lipid peroxidation and ferroptosis—4-hydroxynonenal (4-HNE) and malondialdehyde (MDA)—in tumor tissues from each experimental group." (PMID 41213937, 2025). "Together, these results suggest that USP5 inhibition significantly enhances the efficacy of anti-CTLA-4 immunotherapy in vivo, which might be largely due to decreasing PD-1 and increasing cytotoxic activity of tumor-infiltrating CD8+ T cells." (PMID 37208329, 2023). "Furthermore, we tested whether simultaneously inhibiting USP5-mediated PD-1 expression in cancer cells and CD8+ T cells could further enhance anti-tumor immunity." (PMID 37208329, 2023). "Importantly, ectopic expression of Beclin 1, but not Beclin 1S90+93A, remarkably rescued the tumor growth inhibited by USP5 depletion." (PMID 36528652, 2022). "In addition, USP5 protein level is positively proportionalto PD-L1 expression in NSCLC cancer tissues, indicating USP5 exerts oncogenic roles may partially through promoting tumor immune escape." (PMID 34741014, 2021). "Data from The Cancer Genome Atlas (TCGA) revealed that USP5 is broadly overexpressed across various cancer types, including CRC, with elevated levels observed in both tumor tissues and adjacent non-tumor tissues." (PMID 41213937, 2025). "To explore the effects of USP5 on tumor growth, we implanted LLC cells with or without USP5 knockdown into immune competentC57BL/6 mice." (PMID 34741014, 2021). "Moreover, the tumor-infiltrating CD8+ T cells, but not CD4+ T cells nor Treg cells, was significantly increased in LLC tumors derived from Usp5 cKO mice." (PMID 37208329, 2023).
cancer (55 papers, 2016 to 2025). A tumor composed of atypical neoplastic, often pleomorphic cells that invade other tissues. "USP5 is a component of the regulatory complex associated with the mTORC1 signaling pathway, which is known to be frequently dysregulated in various cancers, including HNSCC." (PMID 40066708, 2025). "Overexpression of USP5 and EphA2 has been linked to various cancers, and both the proteins have attracted considerable attention for the development of new anti-cancer drugs." (PMID 39897046, 2025). "Our findings indicate that USP5 plays a significant role in cancer progression and is associated with clinical outcomes in patients." (PMID 40066708, 2025). "Since STAT2 interacted with USP5 after IFN-β treatment and the phosphorylation-deficient STAT2 lost its binding potential, we then knocked out STAT2 in USP5-deficient cancer cells and found that it eliminated the secretion of p-STAT2 and p-STAT1." (PMID 41321309, 2025). "While Ubiquitin‐specific peptidase 5 (USP5) has been implicated in various cancers, its role in HNSCC remains poorly understood." (PMID 40066708, 2025). "USP5 has also been found to be associated with cancers, including breast, prostate, testicular and urothelial cancers." (PMID 38229092, 2024). "We plotted the receiver operating curve (ROC) to investigate the diagnostic value of USP5 in pan-cancer." (PMID 37268697, 2023). "To investigate the genetic mutations of USP5 in pan-cancer, we used cBioPortal online platform based on TCGA data." (PMID 37268697, 2023). "USP5 belongs to a ubiquitin-specific protease family of deubiquitinases (DUBs) and is associated with various diseases, including cancer." (PMID 36611139, 2023). "We also found that the most frequent genetic alterations type of USP5 was mutation, and the DNA methylation level of USP5 decreased in various cancers." (PMID 37268697, 2023). "The results indicate that USP5 is overexpressed and has certain diagnostic value in various cancer types." (PMID 37268697, 2023). "The result showed that USP5 expression was positively correlated with the infiltration of cancer-associated fibroblasts in CESC, HNSC and HNSC-HPV." (PMID 37268697, 2023). "Interestingly, Western blotting showed increased p-STAT1 and p-STAT2 levels in THP1-MΦ cocultured with IFN-β–treated USP5-deficient cancer cells." (PMID 41321309, 2025). "USP5 has been shown to play an oncogenic role in many types of cancer, but its role and the underlying mechanism in ESCC are unknown." (PMID 40691441, 2025). "USP5 is implicated in the progression of multiple cancer types." (PMID 40390008, 2025). "Importantly, we demonstrated concomitantly high expression of USP5 and PFKP in TNBC patients with advanced TNM stage, highlighting that dysregulated USP5-PFKP signaling was functionally linked to cancer progression in TNBC." (PMID 38217030, 2024). "Here, we observed that USP5 genetic alterations, including mutation and amplification could be found in various cancer types." (PMID 37268697, 2023). "Furthermore, USP5 expression correlated with cancer-associated fibroblasts (CAFs), endothelial cells (EC) and genetic markers of immunodulators in cancers." (PMID 37268697, 2023). "Then, the association between USP5 and specific cancer types was further examined." (PMID 37268697, 2023). "In this study, we explored USP5 expression profiles, diagnostic value, prognostic value, genetic alteration, protein methylation level, immune infiltration, functional states and functional enrichment in pan-cancer by using multiple bioinformatics methods." (PMID 37268697, 2023). "Therefore, future work should extend these studies to other membrane proteins and to substrates implicated in pathologies such as neurodegeneration and cancer in order to understand how USP5 regulates their fates." (PMID 35895711, 2022). "USP5 has been implicated in the tumorigenesis of various types of human cancers." (PMID 35884430, 2022).
cancer (continued). "Together, our data suggest that other overexpressed oncoprotein drivers in cancer cells, which are tightly regulated in normal cells by Lys48-linked polyubiquitination, may be vulnerable to a USP5-targeted inhibitor." (PMID 33658627, 2021). "Finally, USP5 encodes a metabolism protein that is highly expressed in many kinds of cancer, such as breast, prostate and hepatic cancer." (PMID 34692538, 2021). "Similarly, higher USP5 was a risk factor for overall survival in cancers such as HNSC and SKCM." (PMID 41321309, 2025). "In addition, we analyzed the gene mutations and methylation levels of USP5 in pan-cancer." (PMID 37268697, 2023). "Compared to other cancers, USP5’s function shifts from relying on ubiquitination to utilizing the lysosomal pathway, and YBX3 transitions from a pro-survival factor to a ferroptosis-sensitive factor." (PMID 41213937, 2025). "USP5 piqued our interest because it plays a crucial role in promoting malignant tumor progression and exacerbating the inflammatory response." (PMID 41281755, 2025). "Despite extensive research on USP5 in various cancers, its specific function in HNSCC remains largely unexplored." (PMID 40066708, 2025). "By dynamically balancing the stability and degradation of substrate proteins, USP5 reveals its multifunctional regulatory hub role in complex pathological networks such as cancer and inflammation, providing new perspectives for disease-targeted therapy." (PMID 41213937, 2025). "For example, in breast cancer, USP5 is known to enhance cancer cell growth and migration by stabilizing β‐catenin." (PMID 40066708, 2025). "A thorough pan‐cancer evaluation of USP5 expression across 23 cancer types revealed notable overexpression in 18 of them, including HNSCC." (PMID 40066708, 2025). "Several studies have demonstrated that USP5 plays an important role in cancers, including liver, lung, breast, ovarian, and colorectal cancers." (PMID 40136465, 2025). "Several studies have demonstrated that USP5 plays an important role in cancers by targeting its substrates." (PMID 38229092, 2024). "Meanwhile, certain correlations between USP5 and various immunoregulation-related genes were found in many cancer types." (PMID 37268697, 2023). "Using the CancerSEA, we investigated the functional states of USP5 at single cell levels in various cancers." (PMID 37268697, 2023). "USP5 expression was high in most cancers and differed significantly in different molecular and immune subtypes of cancers." (PMID 37268697, 2023). "Generally, our study suggested the potential value of USP5 as an effective target for immunotherapy to enhance the health of cancer patients." (PMID 37268697, 2023). "Further studies on the gene alteration of USP5 and the relationship between DNA methylation and USP5 expression in cancer are needed." (PMID 37268697, 2023). "Given its important role of in regulating γc stability, USP5 can be a potential target for cancer immunotherapy." (PMID 37932447, 2023). "To evaluate the prognostic assessment value of USP5 in pan-cancer, we carried out the Cox proportional hazards model and Kaplan–Meier analysis." (PMID 37268697, 2023). "Ubiquitin specific peptidase 5 (USP5), a deubiquitinase that is involved in multiple cellular processes such as DNA repair, reaction to stress, and cancer, is essential for the production of TNF." (PMID 37228615, 2023).
cancer (continued). "Taken together, our study elucidates the biological significance of USP5 in the diagnosis, prognosis and immune in human pan-cancer." (PMID 37268697, 2023). "Overall, these data not only define a mechanism for PD-1 regulation by ERK/USP5-mediated phosphorylation and deubiquitination, but also provide potential combined therapeutic strategies for cancer patients." (PMID 37208329, 2023). "Ubiquitin-specific proteinase 5 (USP5), a unique member of deubiquitinating enzymes (DUBs) which recognizes unanchored polyubiquitin specifically, could regulate the stability of many tumorigenesis-associated proteins to influence cancer initiation and progression." (PMID 37268697, 2023). "Among these, MLF2, COPS7A, PEX5, DDX47, STRAP and MRPL51 displayed strong correlations with USP5 in most cancer types." (PMID 37268697, 2023). "Meanwhile, USP5 has been demonstrated to be closely correlated with some key molecules and pathways regulating cancer, which indicates the potential value of USP5 as a novel treatment target for cancer." (PMID 37268697, 2023). "Using CancerSEA, we found that USP5 significantly correlated with many biological behaviors of cancers such as apoptosis, cell cycle, DNA damage, metastasis and invasion in several cancer types at single cell levels." (PMID 37268697, 2023). "In line with their researches, our findings from TCGA and GTEx also demonstrated that the expression level of USP5 was significantly higher in most cancers compared with their regular counterparts." (PMID 37268697, 2023). "At last, we further explored the protein expression level of USP5 in pan-cancer using the National Cancer Institute’s CPTAC dataset and the IHC results provided by the HPA dataset." (PMID 37268697, 2023). "Like other USP family deubiquitination enzymes, USP5 is involved in the occurrence and development of various cancers." (PMID 36611139, 2023). "We analyzed the correlation between USP5 expression and molecular or immune subtypes in pan-cancer from the TISIDB database." (PMID 37268697, 2023). "USP5 can facilitate cancer progression, including NSCLC, through deubiquitination and stabilization of several downstream target proteins, including β-catenin, SLUG, FoxM1, Cyclin D1, and PD-L113,15–19." (PMID 36528652, 2022). "By searching the GEPIA2 database, USP5 was found to be highly expressed in most cancers, including GBM." (PMID 34483932, 2021). "Since USP5 is overexpressed in cancer tissues, it can thus potentially serve as a new target for therapeutic interventions." (PMID 34948102, 2021). "Different therapeutic approaches have been used to counteract the increase in FOXM1 in cancers, including targeting of ubiquitin-specific peptidase 5 (USP5)." (PMID 33804240, 2021). "This suggests that cancer cells can activate mechanisms to overcome USP5 inhibition-mediated apoptosis." (PMID 33919439, 2021). "miR-125a suppresses USP5 expression and exhibits antitumor activity by suppressing cancer cell proliferation and inducing apoptosis." (PMID 33919439, 2021). "Several cellular physiological and pathological functions, including development, heat-shock-induced stress response, immune response, cancer, and neuropathology, are regulated by the USP5-mediated deubiquitination of various substrates." (PMID 33919439, 2021). "Ubiquitin-specific protease 5 (USP5) is a deubiquitinating enzyme that functions as an oncoprotein in a variety of human cancers." (PMID 32477134, 2020). "These 84 EOC cases were then divided into USP5 low expression group (n=34) and high expression group (n=50) based on the positive staining ratio of cancer cells." (PMID 31727867, 2019). "The expression and oncogenic roles of ubiquitin specific peptidase 5 (USP5) have been reported in several cancers except EOC." (PMID 31727867, 2019).
cancer (continued). "Among these, USP5 (or isopeptidase T) is a deubiquitinase that regulates different cell cycle modulators and has been shown to play important roles in various cancers." (PMID 31455361, 2019). "USP5 has been reported to be upregulated in several cancers and can activate the β-catenin/c-Myc signaling pathway, which is an important glutaminolytic-associated pathway." (PMID 31371702, 2019). "USP5 loss led to significant increase in p21 (CDKN1A) and p27 (CDKN1B) levels with simultaneous decrease in CyclinD1 in the cancer cells." (PMID 29029505, 2017). "Since USP5 is overexpressed in cancer tissues, it can thus potentially serve as a new target for therapeutic interventions, especially given the fact that deubiquitinases are currently emerging as new class of attractive drug targets in cancer." (PMID 29029505, 2017). "Following transient silencing, viability of the cancer cells was measured using MTT assays, which showed that loss of USP5 expression led to statistically significantly reduced viability of the cancer cells in all four cell lines tested." (PMID 29029505, 2017). "USP5 plays an oncogenic role in various human cancers 28, 35-37." (PMID 39897046, 2025). "Previous studies have indicated that USP5 plays an important role in cancer progression." (PMID 41213937, 2025). "Aberrant expression of USP5 has been documented in various cancer types." (PMID 40066708, 2025). "Thus, it would be interesting to examine the role of USP5 in other cancer malignant phenotypes, such as metastasis and immune evasion, to better assess its therapeutic potential." (PMID 40691441, 2025). "Binding of α-hederin to USP5 prompted us to address whether α-hederin inhibited inflammatory-cancer transformation by targeting USP5." (PMID 41281755, 2025). "Ubiquitin-specific protease 5 (USP5) is an important deubiquitinating enzyme that regulates various physiological functions by removing ubiquitin chains from target proteins and plays a pivotal role in the occurrence and development of various cancers." (PMID 40390008, 2025). "In addition, the gene expression levels of USP5 in CRC cells in the Cancer Cell Line Encyclopedia (CCLE) database were determined to verify the qPCR and western blotting results." (PMID 41281755, 2025). "Several studies have shown USP5 overexpression in some types of cancer." (PMID 38229092, 2024). "Notably, a growing body of evidence suggests that USP5 is widely expressed in various cancers and contributes significantly to cancer progression." (PMID 38217030, 2024). "Ubiquitin-specific peptidase 5 (USP5), which belongs to the peptidase C19 family, preferentially cleaves unanchored polyubiquitin chains: it is considered an oncogene that promotes tumorigenesis in many cancers." (PMID 38531846, 2024). "Several USP5 inhibitors have been developed to treat human cancers." (PMID 38229092, 2024). "Gene enrichment analysis indicated “spliceosome” and “RNA splicing” may be the critical mechanism for USP5 to involve in cancer." (PMID 37268697, 2023). "In addition, USP5 had certain diagnostic value in multiple cancers, and high expression of USP5 generally predicted poor prognosis for cancer patients." (PMID 37268697, 2023). "Here, we explored the role of USP5 in pan-cancer using The Cancer Genome Atlas (TCGA) and Genotype-Tissue Expression (GTEx) database, and we also acquired and analyzed data via various software and web platforms such as R, GEPIA2.0, HPA, TISIDB, cBioPortal, UALCAN, TIMER 2.0, CancerSEA and BioGRID." (PMID 37268697, 2023). "Some previous studies demonstrated that the anti-cancer activity of Degrasyn could be mainly related to the USP5 inhibitory effect." (PMID 36979739, 2023).